CTLA4 (cytotoxic T-lymphocyte associated protein 4)
Diseases named in the same sentence as CTLA4 in open-access papers (continued):
Sharing a sentence is not in itself a finding about the gene and the disease.
tumor (continued). "Furthermore, the interferon response can increase the expression of immune checkpoint molecules on tumor cells, such as programmed cell death ligand 1 (PD-L1) and cytotoxic T lymphocyte-associated antigen 4 (CTLA-4)." (PMID 39697335, 2024). "There are also metabolic inhibitors including IDO and arginase, which are produced by tumor associated macrophages (particularly the M2 phenotype) and upregulation of receptors such as CTLA4 and PD-1, all of which may be contributing to tumor immune escape." (PMID 39108491, 2024). "Some studies have found that NSCLC patients with a high tumor mutational burden (TMB) may respond better to CTLA-4 inhibitors (NCT03527251 and NCT03913923)." (PMID 39308869, 2024). "Cytotoxic T-lymphocyte-associated antigen-4 (CTLA-4) blockers have drawn attention to be one of the early immune checkpoint signal processes within the tumor’s microenvironment because they significantly reduced tumor activity and were used in clinical settings." (PMID 38824143, 2024). "Immune checkpoint proteins, such as programmed-death receptor (PD-1) on T cells, B cells and antigen-presenting cells, PD ligand (PD-L1) on tumor cells, or cytotoxic T-lymphocyte associated protein 4 (CTLA4) are essential components in the host immune response to tumor cells." (PMID 39722028, 2024). "The fact that the percentage of ‘ips_ctla4_neg_pd1_neg’ is greater in the low-risk group than in the high-risk group suggests that patients in the low-risk group have a lesser expression of CTLA-4 and PD-1 immune checkpoint proteins in their tumor microenvironment." (PMID 38517376, 2024). "Analysis of tumors irradiated with carbon ion beams and treated with anti-CTLA-4 showed activation of NK cells, up-regulation of tumor-associated macrophages, TNF and IL-1 response genes, along with improved activity of naive T cells in distant non-irradiated tumors." (PMID 39091498, 2024). "Immunotherapy, which includes ICB therapy that inhibits programmed cell death protein 1/programmed cell death ligand 1 (PD-1/PD-L1) and cytotoxic T lymphocyte-associated antigen-4 (CTLA-4) signaling, tumor vaccines, and ACT, represents a hotspot of cancer therapy." (PMID 38558812, 2024). "RCT001 in synergy with anti-PD-1 and anti-CTLA4 yielded a substantial increase of M1 TAMs, a decreased of TANs (Tumor Associated Neutrophils) and mature TANs (associated with poor prognosis in RCC), accompanied by an increase in activated dendritic cells (DCs) and activated natural killer (NKs)." (PMID 38504270, 2024). "Within TME, they can impair immune clearance of tumour cells through secretion of immunosuppressive cytokines and expression of co-inhibitory cell surface molecules (e.g., CTLA-4) and have been demonstrated to be associated with tumour progression and reduced survival in several cancers." (PMID 39001359, 2024). "Our data present, for the first time, evidence that CTLA-4 c.-1577G>A alters the risk and clinical aspects of CM treated with conventional procedures and may be used for selecting individuals for tumor prevention and patients for distinct treatment." (PMID 39596391, 2024). "Using an MC38 colon adenocarcinoma model, the authors found H. pylori to increase tumor volumes of infected mice and also to reduce the efficacy of anticytotoxic T-lymphocyte-associated protein 4 (CTLA4) and/or programmed death ligand 1 (PDL-1), as well as anti-cancer vaccine treatment." (PMID 38343887, 2024). "In addition, TILs have been shown to express higher levels of CTLA-4, a protein that is linked to aggressive tumor behavior and a poor prognosis." (PMID 39456636, 2024). "Recognizing that neoplasm cells can hijack immune checkpoint pathways like cytotoxic T-lymphocyte-associated protein 4 (CTLA-4) and programmed death-1 (PD-1) to evade the immune system, immune checkpoint blockade therapy was developed as a novel immunotherapeutic approach." (PMID 39766080, 2024).
tumor (continued). "In contrast to CTLA-4–targeted drugs, PD-1 inhibitors cause expansion of T cell clones within the neoplasm, and therefore, autoreactive T cells may develop as part of the immune attack on tumor antigens." (PMID 39105625, 2024). "Potential predictive biomarkers assessed for ICI benefit in GBM patients include tumor PD-L1/2 expression, CTLA-4 expression, mismatch repair deficiency (MMRd), tumor mutation burden (TMB), tumor-infiltrating lymphocytes, tumor-specific antibodies, and T cell functional markers." (PMID 39766048, 2024). "In this sense, it was discovered that the altered probiotic E. coli Nissle strain produced nanobodies that would target immunological checkpoints including cytotoxic t lymphocyte-associated protein-4 and programmed death-ligand 1 intratumorally, as well as a possible tumor-reducing capacity." (PMID 39475915, 2024). "We also found that the clinically relevant immune checkpoint CTLA-4 was significantly higher in low-risk group (P<0.05), indicating that the high-risk group may suffer worse tumor immunotherapy efficacy." (PMID 39091494, 2024). "Immune checkpoint inhibitors (ICIs) targeting cytotoxic T lymphocyte-associated protein 4 (CTLA4), programmed cell death-1 (PD-1), and programmed cell death ligand-1 (PD-L1) have shown promising efficacy in certain tumor types, leading to their entry into the clinic." (PMID 38466449, 2024). "Therefore, the combination of CXD101 and anti-PD1 or anti-CTLA4 treatment causes significant anti-tumor activity compared to anti-PD1 or anti-CTLA4 treatment alone in CRC mouse model." (PMID 37928272, 2023). "In addition, regulatory T cells (Tregs) are considered to secrete suppressive cytokines such as TGF-β and IL-10, express cytotoxic T lymphocyte–associated protein 4 (CTLA-4), and significantly correlate with tumor progression in HNSCC." (PMID 36639648, 2023). "Inhibitory receptors, such as programmed cell death 1 (PD-1), lymphocyte activation gene-3 (LAG-3), T-cell immunoglobulin-3 (TIM-3), and cytotoxic T-lymphocyte-associated protein 4 (CTLA-4), are highly expressed in tumor-infiltrated CD8+ T cells, which results in CD8+ T-cell exhaustion." (PMID 36945005, 2023). "Some mouse studies report that the therapeutic benefit of anti-CTLA-4 depends, at least in part, on Fcγ–receptor-dependent depletion of intratumoral Tregs71, while other studies found that anti-CTLA4 induces proliferation of tumor-associated Tregs in MC38 tumor-bearing mice." (PMID 37089449, 2023). "Additionally, T cell exhaustion derived from programmed cell death protein 1 (PD-1) or cytotoxic T-lymphocyte-associated protein 4 (CTLA-4) immune checkpoint pathways promotes the decrease in anti-tumor activity." (PMID 37371075, 2023). "The immunosuppression caused by the CTLA-4 pathway may limit the effectiveness of cellular therapy based on the tumor antigen-presenting dendritic cells and cytokine-induced killer cells (DC-CIK)." (PMID 36761751, 2023). "Then, effective anti-tumor immune responses are caused by the blockade of CTLA-4 and PD-1." (PMID 38136311, 2023). "This speculation is supported by the fact that CTLA-4 is associated with the recruitment of Tregs into the tumour microenvironment and that Tregs express high levels of CTLA-4." (PMID 36980582, 2023). "Synergistic effects might be achieved with combinations of immune checkpoint inhibitors that target PD-1 on T cells or PD ligand 1 (PD-L1) on tumor cells and anti-cytotoxic T-lymphocyte-associated antigen 4 (CTLA-4) receptor on T cells." (PMID 35836094, 2023). "Therapies targeting the immunological checkpoints programmed cell death-1 (PD-1), programmed cell death ligand-1 (PD-L1), and cytotoxic T-lymphocyte-associated antigen-4 (CTLA-4) have been approved for the treatment of a variety of tumor types, including NSCLC." (PMID 36900362, 2023).
tumor (continued). "Recent progress in understanding tumor–immune dynamics emphasizes ICIs targeting cytotoxic T-lymphocyte-associated protein 4 (CTLA-4) and programmed cell death protein 1 (PDCD1, also known as PD-1), which enhance therapeutic outcomes across several malignancies." (PMID 38003674, 2023). "Immune checkpoint inhibitors with targets like programmed cell death protein 1 (PD-1), programmed death ligand 1 (PD-L1), and cytotoxic T-lymphocyte-associated protein 4 (CTLA-4) have been the mainstay of successful tumor immunotherapy treatments until recently." (PMID 36674038, 2023). "Moreover, the combination of VISTA and CTLA-4 blockade caused tumor regression and inhibited Tregs recruitment." (PMID 36836154, 2023). "In the phase II basket trial of dual anti-cytotoxic T-lymphocyte–associated antigen 4 (CTLA4) and anti-programmed cell death protein 1 (PD-1) blockade (ipilimumab and nivolumab) in rare tumours (DART), 19 patients with high-grade NENs were included (18 with extra-pulmonary primaries)." (PMID 37287870, 2023). "We also developed a CXCL scoring model using principal component analysis and evaluated its effectiveness in predicting immunotherapy response by assessing tumor microenvironment cell infiltration, tumor mutational burden estimation, PD-L1/CTLA4 expression, and immunophenoscore analysis (IPS)." (PMID 36969851, 2023). "The presence of cytotoxic T-lymphocyte-associated protein 4 (CTLA-4) and programmed cell death ligand 1 (PD-L1) in tumor cells may assist tumors in evading the host’s immune system." (PMID 37760441, 2023). "With the same initial settings and obstructing rate of CTLA-4, u=0.76, if the dosage of oncolytic virus is s=9×106 on day 8 as the tumor size reaches to 4×107 and the treatment lasts for 5 days, the susceptible tumor size is 2.2660×107 on day 18 post-implantation." (PMID 36766849, 2023). "Moreover, tumor cells induce anergy or apoptosis in T cells via different immune checkpoint molecules (cytotoxic T lymphocyte-associated protein 4 (CTLA-4) and programmed death 1 (PD1))." (PMID 39282109, 2023). "Furthermore, tumour-associated immunosuppressive Tregs can be depleted using iron-oxide nanoparticles, combining anti-CTLA-4 immunotherapy with photodynamic therapy." (PMID 36980527, 2023). "Programmed cell death 1 (PD-1), programmed cell death 1 ligand 1 (PD-L1), cytotoxic T lymphocyte-associated antigen-4 (CTLA-4) and other targets are specifically targeted by ICIs in order to effectively release immunological brake reactions and suppress tumor immune escape." (PMID 37973916, 2023). "Notably, some TAMCs, such as tumor-associated macrophages (TAMs), myeloid-derived suppressor cells (MDSCs), and tumor-associated monocytes, express immune checkpoints like PD-1 and CTLA-4, which can inhibit T cell and NK cell cytotoxicity." (PMID 37760801, 2023). "Moreover, CTLA4 expression is higher in BC than in normal breast tissue and increased expression levels are associated with node metastasis and globally with higher tumor stage." (PMID 37104271, 2023). "Combining CD47 inhibitors with PD-1/PD-L1 inhibitors or cytotoxic T-lymphocyte–associated antigen 4 (CTLA-4) inhibitors may enhance the anti-tumor immune response by promoting T cell activation and reducing immune suppression in the TME." (PMID 38188674, 2023). "Thus, parameter by exhibits a much stronger correlation with the susceptible tumor size after treatment when the tumor is administered with additional anti-CTLA-4." (PMID 36766849, 2023). "ICIs may restore the ability of cancer immunity to kill tumor cells by blocking some inhibitory molecules of “immune checkpoints” such as PD-1, PD-L1, and cytotoxic T-lymphocyte-associated protein 4 (CTLA-4)." (PMID 37371816, 2023).
tumor (continued). "Less common immunosuppressive cell types in human HCC consist of B cell population expressing PD-1, Th17 cells, CD4+ T cells expressing CCR4 and CCR6, CD14+ DCs expressing CTLA-4 and PD-1, tumor-associated neutrophils, tumor-associated fibroblasts, and type-II T helper cells (Th2)." (PMID 36845131, 2023). "In addition, this review highlights the immune-related adverse events (irAEs) associated with CTLA-4 inhibitors, providing insights into the development of appropriate clinical tumor immunotherapy regimens and intervention strategies." (PMID 37860188, 2023). "Moreover, Bacteroides fragilis was associated with an improved response to anti-cytotoxic T-lymphocyte-associated protein-4 (α-CTLA-4) blockade due to the development of B. fragilis-specific T cells combating the tumor." (PMID 37799719, 2023). "In the in vivo antitumor study, the DOX/anti-CTLA-4/anti-PD-1 co-loaded hydrogel caused higher tumor inhibition efficiency, prolonged mice survival time and increased infiltration of CD8+ T cells in tumors, compared with the hydrogel loaded with DOX or antibodies only." (PMID 37265604, 2023). "Also, critical immune checkpoint genes such as LAG3, PDCD1LG2, CD274, IDO1, PDCD1, and CTLA4 were evaluated because these genes are activated when T cells identify and attach to associated proteins on other cells, such as certain tumor cells." (PMID 37876438, 2023). "In the large two-tumor A20 model, the addition of anti-CTLA-4 to CpG + OX40 caused significant local tumor regression compared to PBS and anti-CTLA-4 alone and caused regression of some tumors at the distant untreated site (LCR 5 of 10 at the treated tumor and 4 of 10 at the distant tumor)." (PMID 37016127, 2023). "Tumor cells express surface molecules associated with tumor immunity, especially immune checkpoints such as PD-L1, CTLA-4, and CD276, which play important roles in regulating antitumor immunity by costimulating or coinhibiting the killing effect of T cells and are thus key targets for immunotherapy." (PMID 37485079, 2023). "However, an association between the expression levels of PD-1 and CTLA-4 and tumor-infiltrating cells exists." (PMID 36874131, 2023). "CTLA-4 deficiency in FoxP3+ cells impairs the inhibitory functions of Treg cells which are considered the biggest obstacle in immunotherapy targets due to their anti-tumor suppressing nature." (PMID 36109471, 2023). "PD-L1, PD-1 and CTLA-4 are expressed at higher levels in the low-risk score group compared with the high-risk score group, suggesting that tumor samples with the low-risk score may tend to have favorable responses to anticancer immunotherapies." (PMID 36869083, 2023). "Considering the intent of improving T cell-mediated destruction of tumor cells via anti-CTLA-4/PD-1 antibodies, it is plausible that increased absolute lymphocyte counts and the presence of tumor infiltrative lymphocytes are associated with improved ICI response." (PMID 37903733, 2023). "It is known that Programmed Cell Death Protein 1 (PD-1) is highly expressed in Tumor-Infiltrating Lymphocytes (TILs) and that PD-1 Ligands (especially PD-L1) and Cytotoxic T Lymphocyte Associated protein 4 (CTLA-4) can be expressed in many cancerous cell types." (PMID 36835456, 2023). "Our study underlines that CTLA-4 expression at the tumor site is associated with better response." (PMID 37563240, 2023). "Furthermore, CD4+ cells recognize tumor cells through the interaction of the T-cell receptor with the tumor antigen that is associated with the MHC-I complex on tumor cells in the presence of costimulatory molecules (CTLA4/CD4+ T cells–B7 tumor cells)." (PMID 37111629, 2023). "Examination of the emergence of acquired resistance in patients with non-small cell lung cancer who initially responded to PD-1 blockade or combined PD-1 and CTLA-4 blockade therapy revealed a decrease in mutation-associated neoantigens in resistant tumors compared with pretreatment tumor samples." (PMID 37614504, 2023).
tumor (continued). "Furthermore, risk scores can also give us hints about the tumor microenvironment and facilitate in predicting the response to the CTLA-4 blocker treatment and other chemotherapeutic agents with potential efficacy such as cisplatin and staurosporine." (PMID 36199434, 2022). "In BC TME, accumulated immunosuppressive cells (e.g., myeloid-derived suppressor cells (MDSCs), tumor-associated macrophages (TAMs) and regulatory T cells (T regs) and evaluated expression of immune checkpoints (e.g., CTLA-4 and PD-1) were reported to induce immune evasion of tumor cells." (PMID 35205125, 2022). "However, this response can be inhibited by the engagement of immune checkpoint proteins expressed on T cells such as programmed death 1 (PD-1) and cytotoxic T-lymphocyte-associated protein 4 (CTLA-4) in lymphoid tissue and in the tumour microenvironment." (PMID 35228677, 2022). "However, the mechanism underlying tumor immunosuppression involves many factors other than the PD-1/PD-L1 pathway, such as CTLA4 and IDO-123." (PMID 36581686, 2022). "Since, it has been discussed that tumor regression caused by anti-CTLA-4 antibodies may rely on a selective reduction of Tregs but not checkpoint blockade." (PMID 36091050, 2022). "In addition, drugs that enhance the killing action of T cells on tumor cells (ipilimumab (targeting cytotoxic T lymphocyte-associated antigen-4(CTLA4)), pembrolizumab and nivolumab (targeting PD1)) have been approved for the treatment of certain solid tumors." (PMID 36387070, 2022). "The research of tumor immune checkpoint inhibitors mainly focuses on three molecules: cytotoxic T-lymphocyte-associated protein 4 (CTLA-4), programmed cell death protein 1 (PD-1) and its ligand PD-L1, such as camrelizumab, sintilimab, pembrolizumab, atezolizumab, tislelizumab, nivolumab, ipilimumab." (PMID 36591442, 2022). "Indeed, the reduction of FOXP3+CD4+ Treg cells in tumor tissue after anti-CTLA-4 mAb (Ipilimumab) treatment was strongly associated with clinical benefit." (PMID 35601491, 2022). "In the immune circulatory system, immune checkpoints such as PD1 and CTLA-4 have inhibitory effects on T cell function, which could help tumors resist apoptosis caused by immune responses and promote tumor progression." (PMID 35842702, 2022). "Currently approved immune checkpoint inhibitors (ICI) are monoclonal antibodies that act by reversing tumor escape caused by two negative regulators of tumor immunity: cytotoxic T-lymphocyte antigen 4 (CTLA-4) and programmed cell death 1 (PD-1) or its ligand, programmed cell death ligand 1 (PD-L1)." (PMID 36552755, 2022). "In tumor immunotherapy, programmed death receptor programmed cell death-1/programmed cell death-ligand 1 (PD-1/PD-L1) inhibitors and cytotoxic T lymphocyte-associated antigen 4 (CTLA-4) inhibitors are the main immune checkpoint inhibitors (ICIs)." (PMID 35686098, 2022). "Peripheral blood can identify biomarkers including circulating immune cells, cytokines, soluble proteins [e.g., soluble cytotoxic T lymphocyte-associated protein 4 (CTLA-4) and soluble PD-1/PD-L1], circulating tumor cells, and tumor cell-derived material (DNA, RNA, and exosomes)." (PMID 35359372, 2022). "According to one study, anti-CTLA-4 antibody therapy improved the prognosis of mice with glycolysis-deficient tumors, indicating that decreased tumor competition for glucose may enhance the therapeutic effect of CTLA-4 blockers." (PMID 35733921, 2022). "Interestingly, a decrease in PD-1 and cytotoxic T-lymphocyte associated protein 4 expression was evident in both tumor-infiltrating and circulating CD8+ T cells, while PD-L1 was downregulated by ZVI NPs treatment in cancer cells in vitro and in vivo." (PMID 35056996, 2022). "However, only a minority of patients robustly and durably respond to these therapies, and while combined targeting of PD-1 and CTLA-4 enhances tumor regression, it is also associated with significantly more adverse events." (PMID 35472220, 2022).